OAZ3 (ornithine decarboxylase antizyme 3)
Description:
Ornithine decarboxylase (ODC) antizyme protein that negatively regulates ODC activity and intracellular polyamine biosynthesis and uptake in response to increased intracellular polyamine levels. Binds to ODC monomers, inhibiting the assembly of the functional ODC homodimers. Does not target the ODC monomers for degradation, which allows a protein synthesis-independent restoration of ODC activity. Stabilizes AZIN2 by interfering with its ubiquitination. Involved in the translocation of AZNI2 from ER-Golgi intermediate compartment (ERGIC) to the cytosol. Probably plays a key role in spermatogenesis by regulating the intracellular concentration of polyamines in haploid germ cells (By similarity).
Synonyms: AZ3; OAZ-t; TISP15
Tractability: No criterion of Open Targets' tractability assessment is met for any kind of drug.
Gene: Protein-coding gene on chromosome 1 (151,762,899 to 151,771,334, forward strand). Ensembl gene ENSG00000143450.
Subcellular location: Nucleus; Cytoplasm
Subcellular location (Human Protein Atlas): Nucleoplasm; Mid piece; Principal piece
Pathways (Reactome):
Metabolism: Metabolism of polyamines; Regulation of ornithine decarboxylase (ODC)
Gene Ontology:
Molecular function: ornithine decarboxylase inhibitor activity; protein binding; ankyrin repeat binding
Biological process: negative regulation of polyamine transmembrane transport; polyamine biosynthetic process; positive regulation of protein catabolic process; spermatogenesis; negative regulation of stress fiber assembly; positive regulation of intracellular protein transport
Cellular component: blood microparticle; nucleoplasm; nucleus; cytoplasm; cytosol; sperm flagellum
Genetic constraint (gnomAD): Loss-of-function variants: 22 observed, 26.69 expected, observed/expected ratio (o/e) 0.82, 90% interval 0.59 to 1.18. The upper end of that interval is the gene's LOEUF score, 1.18, which puts it in group 5 of 6, group 1 being the genes least tolerant of losing a copy. Missense variants: 265 observed, 303.68 expected, observed/expected ratio (o/e) 0.87, 90% interval 0.79 to 0.97. Synonymous variants: 94 observed, 116.65 expected, observed/expected ratio (o/e) 0.81, 90% interval 0.68 to 0.96.
Homologues: Orthologues: chimpanzee OAZ3 (99% identical), macaque OAZ3 (97% identical), dog OAZ3 (89% identical), rabbit OAZ3 (89% identical), mouse Oaz3 (87% identical), rat Oaz3 (83% identical), guinea pig OAZ3 (79% identical), pig OAZ3 (71% identical), zebrafish oaz1b (26% identical). Paralogues in human: OAZ1 (27% identical), OAZ2 (25% identical).
Diseases named in the same sentence as OAZ3 in open-access papers:
OAZ3 is named in the same sentence as 8 diseases in open-access papers, as found by Europe PMC text mining. Sharing a sentence is not in itself a finding about the gene and the disease. The quoted sentences say what the papers report.
infertile (5 papers, 2006 to 2023). "Investigations in male mice have found that loss-of-function mutations in genes involved in the production of headless spermatozoa, such as Spata6, Hook1, Prss21, Oaz3, and Odf1, can cause fertility reduction or infertility." (PMID 36028792, 2022). "The coding sequence of OAZ3 was further screened for polymorphisms by SSCP analysis in the infertile group and an additional 250 general population controls." (PMID 16542438, 2006). "To see if mutations in the OAZ3 gene are responsible for some cases of male infertility, we sequenced and evaluated the genomic DNA of 192 infertile men, 48 men of known paternity, and 34 African aborigines from the Mbuti tribe in the Democratic Republic of the Congo." (PMID 16542438, 2006). "Given its testis-specific expression and the clear link between deregulation of polyamine expression and infertility, OAZ3 is a clear choice for a male infertility candidate gene." (PMID 16542438, 2006). "The coding sequence of OAZ3 was also screened by SSCP in the infertile patients." (PMID 16542438, 2006). "Variant 1, a -239A→G change in the 5' UTR of one infertile patient may also be of significance, as it was not identified in the fertile control group and might lead to reduced levels of OAZ3 being translated." (PMID 16542438, 2006). "Polymorphisms in OAZ3 are not strongly associated with human male infertility, though some of the identified SNPs, like Pro164Ser in exon 5, may contribute to isolated cases of infertility." (PMID 16542438, 2006). "In this context, male mutant mice with disruption of Oaz3 were described as infertile, and their sperm presented alterations in the connection of the head with the tail, but surprisingly, the absence of OAZ3 did not affect polyamine concentrations in testes and epididymides." (PMID 30566531, 2018).
male infertility (3 papers, 2006 to 2018). The inability of the male to effect fertilization of an ovum after a specified period of unprotected intercourse. "Assuming OAZ3 plays an integral role in spermatogenesis, At least two of the identified variants, variants 1 and 20, may be candidates for involvement in male infertility or subfertility." (PMID 16542438, 2006). "In order to obtain further information on the types of testicular cells expressing Azin2, we analyzed the expression of Azin2, Oaz3 and Odc in the testis of two transgenic mouse models presenting male infertility: Atm-null mice and Atr-hypomorphic mice." (PMID 30566531, 2018). "Mutations in the OAZ3 gene are not a common cause of male infertility." (PMID 16542438, 2006).
OAZ3 also shares sentences with these, for which no sentence is quoted: Azoospermia (2 papers); cancer (2); breast carcinoma (1); oligospermia (1); testicular germ cell tumor (1); testicular tumors (1).